POTEB (POTE ankyrin domain family member B)
Synonyms: POTE-15; POTE15; CT104.5; A26B1
Gene: Protein-coding gene on chromosome 15 (21,846,329 to 21,877,735, reverse strand). Ensembl gene ENSG00000233917.
Homologues: Paralogues in human: POTEB2 (100% identical), POTEB3 (99% identical), POTED (95% identical), POTEC (89% identical), POTEI (87% identical), POTEJ (87% identical), POTEF (87% identical), POTEE (87% identical), POTEH (77% identical), POTEG (77% identical), POTEM (77% identical), POTEA (60% identical), and 2 more.
Diseases named in the same sentence as POTEB in open-access papers:
POTEB is named in the same sentence as 6 diseases in open-access papers, as found by Europe PMC text mining. Sharing a sentence is not in itself a finding about the gene and the disease. The quoted sentences say what the papers report.
cystic lymphangioma (1 paper, 2021). "Instead, a mosaic 15q11.1-q11.2 deletion encompassing NBEAP1 and POTEB has been suggested to serve as a factor underlying pathogenesis of diffuse lymphangiomatosis with several typical symptoms, including large cystic lymphangioma over the left abdomen, thigh and vulva." (PMID 33435586, 2021).
fucosidosis (1 paper, 2021). "Also, the 15q11.1-q11.2 microdeletion encompassing several genes, including two OMIM genes, namely NBEAP1 (OMIM # 601889) and POTEB (OMIM # 608912), has not been linked, so far, to fucosidosis." (PMID 33435586, 2021).
POTEB also shares sentences with these, for which no sentence is quoted: B cell CLL (1 paper); diffuse lymphangiomatosis (1); lymphoma (1); Sepsis (1).